BRAF (B-Raf proto-oncogene, serine/threonine kinase)
Diseases named in the same sentence as BRAF in open-access papers (continued):
Sharing a sentence is not in itself a finding about the gene and the disease.
melanoma (continued). "Oncogene-induced suppression of RTKs is one such abnormality that has been observed previously in BRAF V600E+ melanoma and colorectal cancer cells, though through distinct mechanisms to the ones we report." (PMID 39488530, 2024). "The frequent mutation of BRAF, particularly of BRAFV600E, has been reported in benign nevi, the precursors for melanoma genesis." (PMID 38275910, 2024). "In the adult melanoma literature for instance, retreatment with combination MEK and BRAF inhibition is reasonable and is associated with at least temporary response." (PMID 39759151, 2024). "The overexpression of BRAF decreases anoikis induced cell death in melanoma cells through increased phosphorylation of BAD S75." (PMID 38434478, 2024). "BRAF is the only RAF protein that is frequently mutated in cancer cells, and BRAF mutations are found not only in melanoma, but in various other carcinomas as well." (PMID 39200941, 2024). "Downregulating CDKN2A in BRAF-inhibitor-resistant melanoma cells improves the effectiveness of palbociclib." (PMID 38534309, 2024). "Our study, using two experimental methods, immunofluorescence and qPCR analysis, reports on the aberrant LOXL3, SNAI1, and NES expression and their co-expression in dysplastic nevi, melanoma in situ, and BRAF+ and BRAF– melanoma." (PMID 39273022, 2024). "BRAF V600E mutations were predominantly found in low-TMB melanoma tumors, whereas KMT2 mutant melanoma was more likely to have a high TMB compared to wild-type tumors." (PMID 39735011, 2024). "In approximately 50% of cutaneous melanomas, a mutation involving the substitution of valine with glutamic acid at position 600 (V600E) within the BRAF gene occurs, resulting in the uncontrolled proliferation and survival of melanoma cells." (PMID 39229331, 2024). "The authors also analyzed specific genomic profiles within those four melanoma types using previously identified The Cancer Genome Atlas (TCGA) molecular categories: BRAF+, RAS+, NF1+, and triple negative." (PMID 39340537, 2024). "Twenty-three patients with stage IV-M1d, BRAF- or NRASmut melanoma who underwent treatment with regorafenib in combination with BRAF/MEKi were identified." (PMID 39682270, 2024). "Common mutations in melanoma are BRAF and NRAS, but, in addition, approximately 70% of mutations in melanoma involve the mitogen-activated protein kinase (MAPK) pathway." (PMID 38893071, 2024). "Diverse genomic and transcriptomic alterations are found in BRAF inhibitor resistant melanoma, posing a pressing need for convergent, druggable target that reverse therapy resistant tumor with different resistance mechanisms." (PMID 38965534, 2024). "To this purpose we tested three different siRNAs by transient transfection in LOX IMVI BRAF-mutant melanoma cells." (PMID 38472212, 2024). "CM has a high mutation load, and targeted therapy is an important therapeutic method for melanoma with driver gene alterations (i.e., BRAF, NRAS, and KIT)." (PMID 38229080, 2024). "Given the results obtained in patients with advanced melanoma, BRAF inhibitors, such as dabrafenib and vemurafenib, were also evaluated in patients with advanced NSCLC and BRAF mutations, showing promising outcomes." (PMID 39684685, 2024). "Clinically used therapies against BRAF-mutant melanoma have differential off-target effects on the phosphoproteome of endothelial cells, cell-cell junction architecture and vascular permeability." (PMID 38839106, 2024). "Another potential target, a PTEN pseudogene transcript called PTENP1-AS, is expressed in high levels in BRAF inhibitor-resistant melanoma." (PMID 38539548, 2024). "c-KIT mutations, while less common than BRAF and NRAS mutations, play a significant role in certain melanoma subtypes, particularly mucosal and acral melanomas." (PMID 38474231, 2024). "For these experiments, we utilized the BRAFV600E-mutant A375 melanoma cell line, which is sensitive to BRAF inhibitors." (PMID 38213996, 2024).
melanoma (continued). "Prognosis continues to be poor in patients with advanced melanoma progressing after immunotherapy and/or BRAF-targeted therapy." (PMID 39618779, 2024). "We observed a clear upregulation of phospho-ɣH2AX in BRAF WT melanoma cells treated with MEKi trametinib plus CuET, which was higher than with the monotherapies." (PMID 38263136, 2024). "When used RC48 and dabrafenib synergically induced tumor regression together in human BRAF-mutant melanoma cell lines and CDX models." (PMID 38594618, 2024). "To validate the pathway enrichment findings from our genomic analysis at the transcriptional level, we performed GSEA on RNA sequencing data from BRAF mutant melanoma, NSCLC, and CRC." (PMID 38275886, 2024). "MAPK kinase inhibition with BRAF inhibitors such as vemurafenib has been shown to reduce melanoma cell proliferation and promote apoptosis, which has resulted in a clinically observable increase in progression-free survival (PFS) in melanoma patients." (PMID 39519202, 2024). "The best-protected melanoma cell lines were 451LU, followed by MaMel51 cells, with an increase in viability for BRAF-/MEK-inhibitor-treated samples of 42% and 35% respectively compared to cultures without neutrophils." (PMID 38730718, 2024). "Similar findings were observed in melanoma with (Neuroblastoma-RAS) NRAS mutations and colorectal cancer with BRAF mutations, providing additional validation for this study." (PMID 39201332, 2024). "Although immunotherapy (anti‐PD‐1 or anti‐CTLA‐4 antibodies) and targeted therapy (BRAF/MEK inhibitors) have been approved for the treatment of advanced melanoma patients, only a minority of patients derive benefit." (PMID 39135915, 2024). "For example, targeted therapy against BRAF, MEK, and KIT protein kinases has shown improved survival rates in melanoma with a mutation in the BRAF gene." (PMID 39594665, 2024). "Oncogenic mutations in BRAF, NRAS HRAS genes have been described commonly in melanomas of skin and other sites, however, the same at this site has been conspicuously absent." (PMID 38509523, 2024). "Mutational screening revealed the coexistence of BRAF and NRAS mutations in melanomas and nevi and the occurrence of NRAS G12/G13 variants in healthy skin." (PMID 38396984, 2024). "DB-1 is a BRAF mutant, so these results demonstrate the effective dabrafenib inhibition of the BRAF kinase in this melanoma cell type." (PMID 38254853, 2024). "These two categories of drugs have led to a consistent improvement in the therapy of melanoma patients, BRAF-WT or BRAF-mutant, with an advanced stage of development." (PMID 39727691, 2024). "Both Grover- and Darier-like eruptions have been reported as common cutaneous toxicities of systemic therapy with B-RAF inhibitors, including dabrafenib and vemurafenib, which are utilized in the treatment of BRAF mutant cancers such as melanoma." (PMID 39325541, 2024). "Although personalized medicine holds great promise for tailoring treatments for BRAF-mutant melanomas according to individual genetic profiles, the potential of this approach continues to be challenged by tumor heterogeneity." (PMID 39336897, 2024). "BRAF-mutant melanoma patients can be treated with targeted therapy or immunotherapies, and it is not clear which should be provided first." (PMID 38473384, 2024). "Various combinations of BRAF/MEK inhibitors have been approved for patients with BRAF V600-mutant melanoma." (PMID 39336897, 2024). "We also report the different distributions of major oncogenic melanoma alterations (BRAF, NRAS, KIT) among different immune subtype groups." (PMID 38397409, 2024). "RAC1 mutations are insufficient to drive melanoma and are almost always found with other activating MAP kinase hot spot mutations, most frequently NRAS (47%), BRAF, or NF1." (PMID 40396280, 2024). "The upregulation and activation of other receptor tyrosine kinases (RTK) are other ways for melanoma cells to circumvent the activities of BRAF/MEK inhibitors." (PMID 38672652, 2024).
melanoma (continued). "Of note, YUMM1.7 melanoma are by far less immunogenic when compared to RIG-I-sensitive YUMMER 1.7 melanoma, and we provide evidence that combined BRAF/MEK inhibition renders even YUMM1.7 melanoma susceptible to RIG-I agonist-based immunotherapy." (PMID 39165562, 2024). "Melanoma tumors exhibit a wide range of heterogeneity in genomics even with shared mutations in the MAPK pathway, including BRAF mutations." (PMID 39001376, 2024). "Immunotherapy has shown promising results in improving overall survival rates and prolonging the duration of response in patients with BRAF wild-type melanoma." (PMID 39684531, 2024). "The co-mutation profile of class III BRAF-mutant melanomas differs substantially from that observed in class I BRAF-mutant melanomas." (PMID 39727691, 2024). "Accordingly, BRAF mutant melanomas exhibit improved overall survival compared with other cutaneous melanomas." (PMID 38611025, 2024). "70% of melanomas exhibit a mutation in the MAPK pathway, 50% of them include BRAF mutations causing downstream MAPK dysregulation and in consequence permanent cell activation." (PMID 38127894, 2024). "Inhibition of CSF-1 R inhibits rebound of ERK in BRAF-treated melanoma, shifting the TME toward a pro-inflammatory state with subsequent reduction in growth and invasiveness of melanoma cells." (PMID 38533720, 2024). "The receptor-interacting protein kinase (RIPK4) has an oncogenic function in melanoma, regulates NF-κB and Wnt/β-catenin pathways, and is sensitive to the BRAF inhibitors: vemurafenib and dabrafenib which lead to its decreased level." (PMID 38656555, 2024). "In conclusion, the review paper highlights the current landscape of BRAF-advanced therapies in melanoma, focusing on the efficacy and limitations of existing treatments such as BRAF and MEK inhibitors." (PMID 39582535, 2024). "CRAF and ARAF paralogs, the other two RAF protein family members, apart from BRAF, have been identified as mediating resistance upon BRAF inhibitor treatment in melanoma." (PMID 38731852, 2024). "Despite these challenges, tumor-infiltrating lymphocyte (TIL) therapy, as exemplified by lifileucel, has demonstrated notable efficacy against BRAF V600-mutant melanoma." (PMID 39336897, 2024). "The melanoma cell line WM3211, derived from the primary lesion (VGP) and wild type for BRAF, PTEN, N-RAS, and CDK4 and with a mutation at position 576 in the c-KIT gene, showed the lowest tendency to activate caspase-3." (PMID 39596342, 2024). "In this retrospective study conducted at a tertiary cancer center, real-world outcomes from advanced melanoma patients were analyzed approximately a decade after the introduction of immune checkpoint inhibitors and BRAF/MEK-inhibitors into clinical use." (PMID 38473216, 2024). "Yu and colleagues showed that a monoclonal antibody inhibiting CSPG4 either prevented or delayed the development of melanoma cell resistance to the BRAF inhibitor PLX4032 BRAF in vitro." (PMID 39409881, 2024). "To illustrate the complexity of designing individualized therapeutic schemes, we report a case of delayed BRAF-mutant diagnosis, an aggressive forearm melanoma, in a presumed psychiatric patient whose symptoms were caused by cerebral melanoma metastases." (PMID 38611601, 2024). "It has been reported that in melanoma cells with mutated RAS, activation of the MAPK signalling pathway occurs preferentially through CRAF instead of BRAF." (PMID 39340537, 2024). "To date, several drugs targeting BRAF activity have been developed and approved for melanoma treatment." (PMID 39086722, 2024). "We started with two patient melanoma RNAseq studies of equal size: “JCI pre/on/post BRAF inhibitor” (n = 39), and “JCOPO primary melanomas” (n = 39)." (PMID 38791964, 2024). "An overwhelming proportion of melanomas harbor hotspot mutations in either the BRAF or NRAS oncogenes—over 50% and approximately 20–25% of melanomas, respectively." (PMID 38732242, 2024).
melanoma (continued). "The frequency of RAS and NF1 mutations varies depending on the tumor tissue of origin: in melanoma, due to the lower endogenous baseline RAS activity, class III BRAF mutations almost always coexist with mutated RAS or NF1." (PMID 39529955, 2024). "Our first retrospective analysis on the compassionate use of REGO as a monotherapy or combined with other therapies (ICB or targeted therapies) in advanced melanoma patients showed the most pronounced responses when combining REGO + BRAF/MEKi." (PMID 39682270, 2024). "The presence of BRAF mutations, particularly V600E, leads to the activation of the MAPK/ERK signaling pathway, a key driver of cell proliferation and survival in melanoma." (PMID 38474231, 2024). "In the case series reported here, we specifically focus on patients with MBM, who exclusively received triple-targeted therapy of REGO + BRAF/MEKi in BRAFmut melanoma and REGO + MEKi in NRASmut melanoma." (PMID 39682270, 2024). "BRAF WT melanoma cells displayed higher viability than BRAFV600E mutant melanoma cells when treated with vemurafenib." (PMID 39063187, 2024). "The Cancer Cell Line Encyclopedia (CCLE) and Catalogue of Somatic Mutations in Cancer (COSMIC) show that A2058 cells carry both BRAF and MEK mutations and are inherently drug-resistant melanoma cells." (PMID 38822350, 2024). "The results strongly supported the notion that eIF4F negatively controls ERK signaling and eIF4Fi-induced ERK hyperactivation stimulates the EGR1 promoter activity in both BRAF- and NRAS-mutated melanoma cells." (PMID 39436655, 2024). "For melanoma treatment with BRAF inhibitors, metabolic changes, such as increased dependency on lipogenesis, have been suggested as adaptive mechanisms." (PMID 38540310, 2024). "Determining which treatment to provide first in BRAF-mutant carrying melanoma patients is of critical importance, and there is thus a need for predictive biomarkers for these patients to help determine which therapy to use." (PMID 38473384, 2024). "Concerning the mRNA expression, NES was expressed significantly higher in BRAF+ melanoma than in dysplastic nevus and melanoma in situ." (PMID 39273022, 2024). "mRNA vaccines intricately target genes such as BRAF and NRAS mutations to provoke robust immune responses against melanoma-associated antigens." (PMID 39582535, 2024). "Another compound, Trametinib, developed and explored in melanoma therapy, addresses cells that have found ways to bypass BRAF inhibition and activate MEK, the downstream effector protein." (PMID 39055896, 2024). "Nevertheless, in our model, a strong ability to predict BRAF status was revealed for superficially spreading melanoma, although the relation to ulceration was also significant." (PMID 39735251, 2024). "Patients with metastatic BRAF-mutant melanoma have an estimated survival of 6–10 months after diagnosis without current drug therapy intervention." (PMID 38732242, 2024). "Lifileucel is an unmodified, autologous TIL infusion that has shown effective results in a multicenter, international, phase II multicohort study that included patients with BRAF V600-mutant melanoma." (PMID 39336897, 2024). "Heterogeneous responses across different tumor types remain a major issue, as exemplified by the diminished efficacy of BRAF inhibitors in colorectal cancer compared with melanoma due to feedback activation of alternative pathways." (PMID 39518080, 2024). "In this study, we evaluated the coadministration of RC48 and dabrafenib for treating BRAF-mutant melanoma." (PMID 38594618, 2024). "On the genetic side, mutations in genes such as BRAF and NRAS have been implicated in the pathogenesis of melanoma." (PMID 39777336, 2024). "This promotes tumor progression, but, on the other hand, it represents a molecular target for therapy using MAPK inhibitors, such as BRAF and MEK inhibitors, which have shown response rates of up to 76% in patients with melanomas harboring BRAF mutations." (PMID 39204387, 2024).
melanoma (continued). "We showed a synergistic antitumor effect of RC48 and dabrafenib in both in vitro and in vivo models of BRAF-mutant melanoma." (PMID 38594618, 2024). "Our retrospective study has highlighted the value of NGS in detecting BRAF, NRAS mutations and RAF fusions, extending the possibilities for targeted therapies in malignant melanoma." (PMID 38470950, 2024). "present real‐world evidence on the use of anti‐PD‐1 antibodies and BRAF/MEK inhibitors for postoperative adjuvant melanoma in eight Polish centers." (PMID 38212945, 2024). "Three of them had not been detected by previous routine testing (ATM p.R1730* in GE21 pancreatic tumor, NRAS p.Q61K in GE15 melanoma, and BRAF p.V600E in GE01 undifferentiated embryonal sarcoma of the liver)." (PMID 38750555, 2024). "The POLARIS study was conducted to further explore regimens of encorafenib in combination with binimetinib in patients with BRAF V600-mutant melanoma with asymptomatic brain metastases." (PMID 38725995, 2024). "The results confirmed alantolactone had cooperating therapeutic effects with BRAFi + MEKi on BRAF mutant melanoma in vivo." (PMID 38822350, 2024). "Study also showed that activation of HER3/STAT3/SOX2 pathway was the mechanism of resistance against MAPKi in BRAF mutant melanoma cells." (PMID 38822350, 2024). "Some trials have investigated efficacy and safety of triple therapy combinations (BRAF/MEK inhibition in combination with anti-PD-1/PD-L1) in BRAF-mutant melanoma but have in general shown high rates of TRAEs." (PMID 39337530, 2024). "Extensive studies have recognized diverse pathways that drive the resistance against BRAFi in BRAF-mutant melanoma, denoting that durable control of resistance would be challenging." (PMID 39238805, 2024). "Although all BRAFi efficiently impeded ERK phosphorylation in BRAF-mutant and BRAF-WT melanoma cells, their effect on MAPK signaling in endothelial cells resembled the effect in melanoma cells with upstream NRAS mutations." (PMID 38839106, 2024). "Combination therapies targeting multiple pathways, such as DNA-damaging agents and BRAF inhibitors, have demonstrated enhanced tumor cell death both in vitro and in vivo, while also preventing melanoma re-growth after treatment discontinuation." (PMID 39596009, 2024). "Immunotherapy is also a treatment option for BRAF-mutant melanoma that includes treatments involving interleukin 2, interferons, and programmed cell death protein 1 (PD-1)." (PMID 39336897, 2024). "Currently, the standard of care for the treatment of BRAF V600E-mutant melanoma includes a combination of vemurafenib (RAFi) plus cobimetinib (MEKi) plus atezolizumab (anti-PD-L1 mAb)." (PMID 38539548, 2024). "The prognosis and natural evolution of AJCC stage IV-M1d, BRAF-wild-type melanoma with active brain metastasis progressing on ICB is very poor." (PMID 39314226, 2024). "In melanomas, HSP70 protects cells from apoptosis and positively regulates BRAF pathways, creating favorable conditions for further melanoma development." (PMID 39519202, 2024). "Treatment with FAK inhibitors has been shown to overcome CAF-mediated resistance to BRAF inhibitors in melanoma." (PMID 38730588, 2024). "In melanomas showing Spitz-like features, the presence of VE1 and/or NRAS Q61R IHC helps to confirm the conventional melanoma pathway alteration in BRAF V600E and/or NRAS Q61R, respectively." (PMID 38247727, 2024). "Melanoma cells have been shown to exhibit substrate modulus dependence in vitro by increasing f-actin stress fiber formation and forming stiffness-dependent focal adhesions, which may regulate susceptibility to inhibitor therapy based on survival signaling via BRAF-MEK-ERK and/or PI3K-AKT." (PMID 39594665, 2024). "On the other hand, this study represents a robust and homogenous cohort of advanced melanoma patients treated with BRAF/MEKi and ICIs beyond clinical trials." (PMID 38473216, 2024).